ABL1 (ABL proto-oncogene 1, non-receptor tyrosine kinase)
Diseases named in the same sentence as ABL1 in open-access papers (continued):
Sharing a sentence is not in itself a finding about the gene and the disease.
myeloid neoplasm (24 papers, 2015 to 2026). Proliferation of myeloid cells originating from a primitive stem cell. "AML with BCR/ABL1+ had been included as a separate provisional entity in 2016 by WHO classification of myeloid neoplasms." (PMID 37234472, 2023). "We characterized genomic alterations in an individual with ETV6::ABL1 gene-fusion-positive myeloid neoplasm using various genomic technologies." (PMID 37895201, 2023). "In 2016, WHO has included AML with BCR/ABL1+ gene as a separate provisional entity in its latest classification of myeloid neoplasms." (PMID 37234472, 2023). "Such dense clusters of hypermethylation included the translocated ABL1 promoter, the promoter regions of Wilms tumor 1 (WT1), a transcription factor overexpressed in myeloid malignancies, and the promoter of the ZNF577 gene that encodes a zinc finger protein." (PMID 29575763, 2018). "Even if diagnostic criteria are well specified in the WHO classification, in clinical practice, distinguishing aCML from the other BCR/ABL1 negative myeloid neoplasms could be challenging." (PMID 34684141, 2021). "While all the mature lymphoid neoplasms show an improvement over time, no clear increase is observed for the myeloid neoplasms: AML, MDS, MDS/MPN, and BCR::ABL1-negative MPN (PV, ET, PMF), with the exception of CML." (PMID 37686664, 2023).
non-small cell lung carcinoma (24 papers, 2012 to 2025). A group of at least three distinct histological types of lung cancer, including non-small cell squamous cell carcinoma, adenocarcinoma, and large cell carcinoma. "Examples include the BCR::ABL1 gene fusion in patients with CML and ALK fusions (e.g. EML4::ALK) in non-small-cell lung cancer." (PMID 41421967, 2025).
chronic neutrophilic leukemia (20 papers, 2018 to 2025). A rare chronic myeloproliferative neoplasm characterized by neutrophilic leukocytosis. "Its differential diagnosis includes BCR::ABL1 negative CML and other MPNs such as chronic neutrophilic leukemia (CNL) and chronic eosinophilic leukemia." (PMID 38992589, 2024).
eosinophilia (20 papers, 2014 to 2026). "In contrast, BCR::ABL1 or tyrosine kinase fusions associated with myeloid/lymphoid neoplasms with eosinophilia, as well as JAK2, MPL, and CALR mutations, are used as exclusion criteria." (PMID 38992589, 2024). "Myeloid (and lymphoid) neoplasms with eosinophilia are associated with rearrangement of the tyrosine kinase (TK) genes, namely PDGFRB, PDGFRA, FGFR1, JAK2, FLT3, and ABL1 (excluding BCR-ABL1)." (PMID 39156600, 2024). "The ETV6::ABL1 fusion was recently included in the genetic abnormalities defining the disease category of myeloid/lymphoid neoplasms with eosinophilia and tyrosine kinase gene fusions (MLN-TK)." (PMID 39066837, 2024). "Eosinophilia, a morphological hallmark of MLN-TK with ETV6::ABL1, persisted throughout the disease progression in our case, from the MPN phase to the 1st blast phase." (PMID 39066837, 2024). "The ETV6::ABL1 fusion defines a subgroup of myeloid/lymphoid neoplasms with eosinophilia and tyrosine kinase gene fusions." (PMID 39066837, 2024). "The MLN-TK with ETV6::ABL1 shares common clinicopathological features with chronic myeloid leukemia, such as eosinophilia and response to tyrosine kinase inhibitor (TKI) therapy, due to the structural and functional similarity of the fusion proteins." (PMID 39066837, 2024). "FIP1L1::PDGFRA and ETV6::ABL1 fusion genes share striking clinical and morphological similarities including male predominance, the relative frequency of eosinophilia and monocytosis, the median absolute number of eosinophils, and presentation or progression to BP including EMD." (PMID 37454239, 2023). "This category name has changed from the previous “myeloid/lymphoid neoplasms with eosinophilia and rearrangement of PDGFRA, PDGFRB or FGFR1, or with PCM1::JAK2” (MLN-eo), to specify the underlying molecular genetic changes and to include cases with ETV6::ABL1, FLT3 fusions or other TK fusion genes." (PMID 37454239, 2023). "The frequency of eosinophilia varied significantly depending on the specific fusion gene involved: it was present in 91% of patients with FIP1L1::PDGFRA and 100% with ETV6::ABL1, but only in 43% of those with PDGFRB, FGFR1, or JAK2 fusion genes." (PMID 41530508, 2026). "Previous studies have also shown the presence of eosinophilia in all MPN and AML cases with ETV6::ABL1." (PMID 39066837, 2024). "BCR::ABL1 is found in 95% of CML, in which leukocytosis with granulocytic precursors, eosinophilia and basophilia are the most preponderant abnormalities on the hemogram." (PMID 36980287, 2023). "After ruling out the hypothesis of non−hematologic origin, testing for gene rearrangements associated with clonal eosinophilia, such as BCR::ABL1, PDGFRA, PDGFRB, FGFR1, PCM1::JAK2, and JAK2::V617F, did not yield any definitive clues." (PMID 38992589, 2024). "Nearly 100 different TK fusion genes, involving at least six TK (PDGFRA, PDGFRB, FGFR1, JAK2, ABL1, FLT3), have been identified in distinct MLN with or without eosinophilia." (PMID 39037514, 2024). "To date, more than 70 different TK fusion genes with recurrent involvement of at least six TK (PDGFRA, PDGFRB, FGFR1, JAK2, ABL1, FLT3) have been identified in clinically and morphologically distinct MLN with or without eosinophilia." (PMID 37454239, 2023). "In 81/135 (60%) evaluable patients, hypereosinophilia (>1.5 × 109/l) was observed in 40/44 (91%) FIP1L1::PDGFRA and 7/7 (100%) ETV6::ABL1 positive patients but only in 13/30 (43%) patients with PDGFRB, FGFR1, and JAK2 fusion genes while 9/30 (30%) patients had no eosinophilia." (PMID 37454239, 2023). "Therefore, an RNA-based study capable of sensitively detecting ETV6::ABL1 should be used for diagnostic evaluation, especially in patients with MPN featuring eosinophilia and lacking the BCR::ABL1, considering clonal burden and disease phenotype in the interpretation of results." (PMID 39066837, 2024).
B-cell acute lymphoblastic leukemia (19 papers, 2014 to 2025). A neoplasm of lymphoblasts committed to the B-cell lineage, typically composed of small to medium-sized blast cells. "Breakpoint cluster region (BCR)-Abelson murine leukemia viral oncogene homolog 1 (ABL1)+ precursor B-cell acute lymphoblastic leukemia (B-ALL) is characterized by blockade of B-cell differentiation." (PMID 31464654, 2019). "The RCSD1 gene has recently been identified as a novel gene fusion partner of the ABL1 gene in cases of B-cell Acute Lymphoblastic Leukemia (B-ALL)." (PMID 26600955, 2015).
prostate carcinoma (19 papers, 2007 to 2024). A carcinoma that arises from epithelial cells of the prostate gland. "Enhanced expression and activation of ABL1 kinase have been implicated in the progression of a wide variety of solid tumor types where c-Met activation also occurs, including breast and prostate cancers." (PMID 27086914, 2016). "ABL1 has been previously reported to act as a switch between cellular, invasive and proliferative, states and can either promote invasion and prostate cancer aggressiveness, or inhibit its progression, depending on the signal." (PMID 32933107, 2020). "To determine if Abl is a functionally relevant target of miR-4723 in prostate cancer, we inhibited Abl1 expression using siRNA to see if Abl1 knockdown functionally mimics the effects of miR-4723 overexpression." (PMID 24223753, 2013). "Indeed, similar to the known SPOP substrate ERG, the protein abundance of ABL1 increased in DU145 prostate cancer cells upon treatment with either the proteasome inhibitor MG132 or the neddylation inhibitor MLN4924." (PMID 34795215, 2021). "In addition, our study has identified a new miRNA based mechanism regulating Abl1 and Abl2 expression in prostate cancer." (PMID 24223753, 2013). "Then, we evaluated the gene expression profiles for the six HUB nodes (ABL1, EP300, FYN, MYC, PSMB2, and SRPK2) in all the prostate cancer cells, compared to normal prostate EPN cells." (PMID 32933107, 2020). "The rearrangements of UBAP2L and EHMT1 have been reported in liver, lung, breast, ovary, and prostate cancer but not in hematological malignancies, and ABL1 or BCR has not been reported as their partner genes." (PMID 39596557, 2024). "Additionally, RT can stimulate the tyrosine kinase ABL1 in prostate cancer cells, leading to its translocation from the cytoplasm to the nucleus where it binds to the MCSF gene promoter, thus promoting MCSF secretion from prostate cancer cells." (PMID 39165639, 2024).
multiple myeloma (18 papers, 2005 to 2025). "Although nuclear ABL1 triggers cell death via interaction with YAP1 in normal cells, low YAP1 levels in myeloma – due to genetic inactivation or reduced expression – prevent nuclear ABL1-induced apoptosis (left)." (PMID 31139207, 2019). "The majority of these studies have focussed on solid tumors, however there are reports in haematological malignancies including multiple myeloma and T-ALL, and we have previously reported a role for SphK2 in B lineage ALL using a BCR/ABL1-dependent model." (PMID 29441205, 2018).
primary myelofibrosis (18 papers, 2012 to 2026). Myelofibrosis with myeloid metaplasia is a myeloproliferative disease with annual incidence of approximately 1 case per 100,000 individuals and age at diagnosis around 60 (an increased prevalence is noted in Ashkenazi Jews). "PMF and post-ET/PV MF are the BCR::ABL1-neg MPNs categories with the worst survival rates in adults and can only be cured by allo-HSCT, which can induce molecular remission and resolution of bone marrow fibrosis." (PMID 38627449, 2024).
colon cancer (15 papers, 2010 to 2025). "The aim of this study was to elucidate the role of ABL1 to obtain information on colon cancer gene mutation." (PMID 32850446, 2020). "The aim of this study was to elucidate the role of ABL1 using high-throughput DNA sequencing technology to obtain information on colon cancer gene mutation." (PMID 32850446, 2020). "While most of the specific amino acid mutations mirror what is seen on the COSMIC database, some unique colon cancer gene mutations were found, which include ABL1-F359V, AKT1-E17K, MET-R970C, and MET-T992I." (PMID 20233444, 2010). "For instance, RAC3 is regulated by ABL1, and this enhanced regulation has been shown to contribute to chemoresistance in colon cancer cells and support the maintenance of cancer cell stemness." (PMID 40585960, 2025). "Mutations in ABL1 and MET, not previously identified in colon cancer, were identified, and 13 other genes were screened and found not to be mutated in hot spot locations." (PMID 20233444, 2010).
Splenomegaly (15 papers, 2016 to 2025). Abnormal increased size of the spleen. "We demonstrate that MC deficiency prevents BCR::ABL1 induced splenomegaly and elevation of pro-inflammatory cytokines." (PMID 37161070, 2023). "Importantly, we demonstrate that genetic mast cell deficiency conferred by the Cpa3Cre allele prevents BCR::ABL1 induced splenomegaly and impairs the production of pro-inflammatory cytokines." (PMID 37161070, 2023). "Remarkably, and in contrast to the retroviral model, BCR::ABL1-positive MC-deficient mice showed no signs of splenomegaly." (PMID 37161070, 2023). "We identified 39 individuals (0.019%) with two or more supporting reads of BCR::ABL1 or ABL1::BCR, most of whom had a diagnosis of CML, haematological features suspicious of CML (for example, splenomegaly or basophilia) or unspecified haematological issues." (PMID 40205062, 2025).
hepatocellular carcinoma (14 papers, 2009 to 2024). A malignant tumor that arises from hepatocytes. "Studies examining Kaplan–Meier survival curves of lung, breast, colorectal, hepatocellular carcinoma patients of varying subtypes found that elevated ABL1 and/or ABL2 is associated with decreased metastasis-free survival and/or lower overall survival." (PMID 34022881, 2021). "The role of ABL1 in hepatocellular carcinoma (HCC) is still unclear." (PMID 34484330, 2021). "It was reported that hepatocellular carcinoma (HCC) samples have increased levels of ABL1 compared with nontumor liver tissues, and overexpress ABL1 correlates with shorter survival times for patients." (PMID 36575369, 2022).
leukocytosis (14 papers, 2015 to 2025). "As previously published, testing for BCR::ABL1 fusion in patients with known BCR::ABL1-negative MPN was prompted by new-onset leukocytosis, whereas testing for driver mutations in patients with known CML was prompted by new-onset thrombocytosis." (PMID 40906032, 2025). "All ETV6::ABL1 positive patients (n = 7; male 6/7; median age 30 years, range 20–74) presented with leukocytosis >10 × 109/l (median 62 × 109/l, range 20.9–143)." (PMID 37454239, 2023). "The research of BCR::ABL1 is an important step for differential diagnosis in the case of persistent leukocytosis and/or thrombocytosis (after eliminating reactional events), notably, if there are few myeloid precursors." (PMID 36980287, 2023). "Therefore, in case of persistent thrombocytosis without leukocytosis and negative driver mutations, BCR::ABL1 will be researched to avoid missing atypical presentation of CML." (PMID 36980287, 2023).
myelofibrosis (14 papers, 2013 to 2025). A partial or complete replacement of the bone marrow stroma by fibrous tissue. "The patient was diagnosed with CML blast crisis of the acute megakaryoblastic leukemia subtype (M7), presenting with BCR/ABL1 fusion gene positivity, complex karyotypic abnormalities, and secondary myelofibrosis." (PMID 41341402, 2025). "In rare cases, patients with primary myelofibrosis may undergo leukemic transformation involving the emergence of a BCR::ABL1-positive clone." (PMID 40734882, 2025). "In adults PMF and post-ET/PV myelofibrosis (post-ET/PV MF) are BCR::ABL1-neg MPNs with the worst survival rates, but allo-HCT can cure a substantial number of patients, especially those younger than 70 years and with a median survival expectation of less than 5 years." (PMID 38627449, 2024). "In children and adolescents myelofibrosis (MF) is the rarest type of BCR::ABL1-neg MPNs, and so far there was no study analysing the outcomes of allo-HCT in a larger group of paediatric patients with MF, and therefore the data on allo-HCT outcomes in them remain casuistic and scant." (PMID 38627449, 2024). "On top of this, quantitation of mutant burden in the patients can provide important clinical information such as transformation to myelofibrosis and drug responses in the patients with BCR::ABL1-negative MPNs." (PMID 37629188, 2023).
colorectal cancer (13 papers, 2014 to 2025). A primary or metastatic malignant neoplasm that affects the colon or rectum. "For example, the increased activity of ABL1 (P = 2.20×10−219) is proved to be associated with decreased metastasis-free survival and/or lower overall survival in colorectal cancer." (PMID 40585960, 2025). "ABL1 then phosphorylates the Rac/RhoGef protein TRIO on Y2681 causing Rho activation and colorectal cancer cell invasion." (PMID 34022881, 2021). "With a quantitative real-time PCR array, we identified several oxidative stress-related genes differentially expressed, and ABL1 was significantly elevated in both GC patients with depression and colorectal carcinoma patients with depression." (PMID 31396300, 2019). "Our preliminary study confirmed that ABL1 was expressed notably higher in GC and colorectal carcinoma patients with depression." (PMID 31396300, 2019). "In our previous work, we found that ABL1 was upregulated in patients with both GC/colorectal carcinoma and depression, and some kinds of cytokines like Leptin-LepRb and COX2 are abnormally expressed." (PMID 31396300, 2019). "In colorectal cancer, when the tumor suppressor gene Aes is knocked out NOTCH1 becomes activated and stimulates ABL1 activity." (PMID 34022881, 2021). "In non-Aes mutant colorectal cancer, ABL1 can also increase NOTCH1 and MYC protein levels leading to enhanced tumor growth." (PMID 34022881, 2021). "Furthermore, ABL1 is highly expressed in colorectal cancer cells, and the absence of ABL1 inhibits cell proliferation and abnormally elevated apoptosis in two cell lines, SW480 and HCT-116, in models of colorectal cancer." (PMID 40014587, 2025).
Thrombocytosis (13 papers, 2012 to 2025). Increased numbers of platelets in the peripheral blood. "In the present study, we report a case of CML (41 years, female) with extreme thrombocytosis at onset, with the variant Ph chromosome and rare e14a3 (b3a3) BCR::ABL1 transcript." (PMID 36354705, 2022). "In CML patients, the persistence or occurrence of thrombocytosis, despite WBC decrease and good molecular BCR::ABL1 response under TKI, should alert clinicians to perform molecular screening for Ph-negative MPN, including JAK2, MPL, and CALR mutations." (PMID 38596359, 2024).
glioblastoma (12 papers, 2013 to 2025). The most malignant astrocytic tumor (WHO grade IV). "Additionally, the study showed downregulation of BRCA1 and MMR-dependent ABL1 gene expression in IMR-90 cells in comparison to the increased expression of BRCA1 and ABL1 in glioblastoma cells; indicating involvement of the HRR and MMR pathways." (PMID 28703770, 2017).
amyotrophic lateral sclerosis (11 papers, 2012 to 2025). Amyotrophic lateral sclerosis (ALS) is a neurodegenerative disease characterized by progressive muscular paralysis reflecting degeneration of motor neurons in the primary motor cortex, corticospinal tracts, brainstem and spinal cord. "ABL1 hyperactivation has been shown in other neurodegenerative diseases with inhibitor treatment generally reported as beneficial for Alzheimer’s disease (AD), Niemann-Pick Type C (NPC), and amyotrophic lateral sclerosis (ALS)." (PMID 33117143, 2020).